ERBB3 (erb-b2 receptor tyrosine kinase 3)
Diseases named in the same sentence as ERBB3 in open-access papers (continued):
Sharing a sentence is not in itself a finding about the gene and the disease.
melanoma (continued). "Finally we complement our study by showing with a liquid biopsy assay that circulating tumor cells (CTCs) from melanoma patients undergo upregulation of ErbB3 phosphorylation in vivo shortly after initiation of therapy." (PMID 31557826, 2019). "Thus, our work discovers a novel phosphorylation-dependent regulatory mechanism of SOX10 transcription activity and completes an ERK1/2/SOX10/FOXD3/ERBB3 axis that mediates adaptive resistance to RAF inhibitors in mutant BRAF melanoma cells." (PMID 29295999, 2018). "Specific inhibition of ERBB3 by either shRNA or a novel neutralizing antibody in combination with fucoidan partly recapitulated these effects, reiterating the ERBB3 pathway is a major player in melanoma cell survival." (PMID 28060735, 2017). "ERBB3 has recently emerged as an important player in melanoma." (PMID 28060735, 2017). "Another study identified that in B-RAF mutated melanoma cells, MEK inhibitor mediated activation of AKT may be enhanced by increased ERBB3 signalling." (PMID 29156708, 2017). "Thus, our results indicate a regulatory role of GH on expression of HGF, MET and ERBB3 in human melanoma cells." (PMID 28223541, 2017). "Importantly, the enhancing cell killing effects of fucoidan can be recapitulated by inhibiting ERBB3 by either a specific shRNA or a novel, selective ERBB3 neutralizing antibody, reiterating the key roles played by this receptor in melanoma." (PMID 28060735, 2017). "Similarly, in melanoma, we have demonstrated that ERBB3/ERBB2 is a key survival signaling unit that acts mostly by activating AKT." (PMID 28060735, 2017). "Hence, ERBB3 represents an intriguing target that can potentially affect multiple aspects of melanoma pathogenesis." (PMID 28060735, 2017). "Taken together, these results indicate a combination therapy involving the clinical drug lapatinib or ERBB3 inhibitors, and the natural compound fucoidan may be a novel, safer treatment option for melanoma patients characterized by increased ERBB activity." (PMID 28060735, 2017). "Additionally, the ERBB family members EGFR, ERBB1, ERBB2 and ERBB3 are known to be involved in driving several oncogenic processes in melanoma." (PMID 28223541, 2017). "Indeed, lapatinib, a clinical ERBB2 and EGFR inhibitor, effectively inhibited the ERBB3/ERBB2 pathway and importantly, delayed melanoma tumor growth in both mutated and wild type BRAF cells." (PMID 28060735, 2017). "An inverse relationship between MITF and ERBB3 protein expression levels was observed in our cell panel, and this was particularly evident in the immortalized melanocyte cell line Hermes 4C, and in the melanoma cell lines WM983B and WM115." (PMID 27391157, 2016). "Hence it is possible that indeed ErbB3 is the principal receptor involved in early adaptive responses of melanoma cells upon exposure to inhibitors of the MAPK pathway." (PMID 26208478, 2015). "We next assessed the effect of the anti-ErbB3 antibodies A3 and A4 on melanoma cell growth in vivo." (PMID 26208478, 2015). "We have previously shown that both antibodies inhibit NRG1 binding, NRG1-induced pHER3 stimulation, ligand-induced signaling and ligand-induced melanoma cell proliferation through binding to different epitopes, one of which (A3) has been mapped to the ErbB3 heterodimerization loop with other ErbBs." (PMID 26208478, 2015). "In addition, transcriptional upregulation of erbB3 has been shown to involve in resistance to RAF/MEK inhibitors in the treatment of melanoma and thyroid carcinomas." (PMID 24886126, 2014). "Interestingly, the increased erbB3 in melanoma or thyroid cancers also depended upon erbB2 to activate the downstream signaling Akt or MAPK." (PMID 24886126, 2014). "Also, FOXD3-dependent upregulation of the EGFR family member ERBB3 was described after BRAF- or MEK inhibition in melanoma cells, resulting in enhanced responsiveness to ERBB3 ligands and the sensitization towards the BRAF inhibitor PLX4720 by lapatinib." (PMID 24970815, 2014).
melanoma (continued). "We first observed in these cells that the anti-ErbB3 antibody A3 was able to induce strong ErbB3 downregulation as previously shown in melanoma cells and that the antibody was able to decrease, albeit to a variable extent, heregulin-induced pErbB3, pAKT and pERK signaling." (PMID 23896512, 2013). "Therefore, inhibition of ErbB3 with monoclonal antibodies is expected to impair the growth promoting effect of mutant ErbB4-ErbB3 heterodimers in melanomas." (PMID 22889873, 2012). "Notably, a meta-analysis of 12 studies found that elevated ErbB3 protein expression was associated with worse overall survival not only in BRCA patients, but also in patients with colorectal, gastric, melanoma, ovarian, head and neck, pancreatic, and cervical cancers." (PMID 41348103, 2026). "Importantly, the cell-killing effects of fucoidan could be enhanced by inhibiting ERBB3 with either a specific shRNA or a novel, selective ERBB3 neutralizing antibody, underscoring the pivotal role played by this receptor in melanoma." (PMID 38186578, 2023). "Specifically, we have shown that ERBB3 is highly active (phosphorylated) in up to 70% of melanomas regardless of whether they carry mutated or wild type BRAF, the most common oncogenic driver in melanoma." (PMID 28060735, 2017). "HER3/ErbB3 is a member of the human epidermal growth factor receptor (EGFR) family and HER3 expression has been correlated with tumor progression and reduction of patient survival in pancreatic, breast, ovarian and gastric cancer, in head and neck squamous cell carcinoma and in melanoma." (PMID 27203743, 2016). "While melanoma cell populations that express high levels of RTK may be selected and expand following MAPK inhibitor treatment, FOXD3 is increased by BRAF inhibitor treatment and transcriptionally induces ERBB3 expression, providing an early adaptive resistance response in melanoma." (PMID 26426052, 2015). "ErbB3 might also be the preferred dimerization partner for EGFR in melanoma and pancreatic cancer." (PMID 24886126, 2014). "Conversely, subpopulations of cells with a proliferative phenotype preferentially express ERBB3; with ERBB1 and ERBB3 expression shown to be mutually exclusive in melanoma cell lines." (PMID 37181747, 2023). "Targeting the ErbB3/ErbB2 pathway with neutralizing antibodies seribantumab (MM-121) and pertuzumab counteracted the protective effects of CAF and improved melanoma cell drug responsiveness." (PMID 37784082, 2023). "NRG1, highly expressed in fibroblasts and CAF, is a ligand for ErbB3, and fibroblast-derived NRG1 can attenuate the effect of RAF inhibitors on melanoma cells." (PMID 37784082, 2023). "In YAP1-activated melanoma cells, SLC35B2 knockout abrogated HS surface expression and limited activity of YAP1-stimulated RTKs including ERBB3, EGFR, and AXL." (PMID 35798875, 2022). "HER2 can form functional dimers with HER3/ERBB3 or with EGFR, both of which were also found to be enriched in MVs from melanoma cells with supernumerary centrosomes." (PMID 36875714, 2022). "In conclusion, our study demonstrated that LRIG1‐TG mice develop melanocytic skin tumors during chemical skin carcinogenesis and a deletion of LRIG1 in human melanoma cells reduces EGFR and ERBB3 expression after EGF stimulation." (PMID 33786987, 2021). "The NRG1/ErbB3/AKT axis has been shown to be involved in adaptive drug resistance in several tumour types, including, breast, lung, prostate, cancer and melanoma." (PMID 31557826, 2019). "Enhanced NRG1/ERBB3 signaling activates the PI3K/AKT pathway and protects melanoma cells against the cytotoxic effect of RAF inhibitors." (PMID 29295999, 2018). "To test this, we evaluated the ERBB3/AKT signaling and vemurafenib-induced apoptosis in melanoma cells depleted of SOX10." (PMID 29295999, 2018). "We previously demonstrated that melanoma relies on the activation of ERBB signaling, specifically of the ERBB3/ERBB2 cascade." (PMID 28060735, 2017).
melanoma (continued). "To investigate the relationship between SOX10, MITF, FOXD3, ERBB3 and NRG1 in patient samples, we utilized The Cancer Genome Atlas (TCGA, SKCM), which contains a set of 474 melanoma patient samples." (PMID 27391157, 2016). "Upregulation of various RTKs or their ligands have been reported in MAPK-inhibitor resistant melanoma, including PDGFRβ, IGF-R1, HGF, FGFR2, NRG1 and the EGFR family (EGFR, ERBB2, ERBB3, ERBB4)." (PMID 26426052, 2015). "We next assessed whether the combination of the anti-ErbB3 antibodies A3 and A4 is more potent than single antibody treatment to block vemurafenib-induced activation of the pErbB3/pAKT axis and to synergize with vemurafenib in the inhibition of melanoma cell growth." (PMID 26208478, 2015). "Multiple RTKs can be co-expressed in resistant melanoma cells, with expression clusters involving EGFR, ERBB3, AXL and PDGFR being identified leading to multiple resistance drivers that are difficult to target with single drugs." (PMID 26426052, 2015). "In these analyses, we were able to confirm expression of transcripts specific for CD63, ErbB3, CD44, and IGF-1-R in melanoma cells and melanoma cell lines in all samples tested." (PMID 24489649, 2014). "Interestingly, treatment of SKMEL28-YAP5SA cells with high doses of UFH or the LMWH nadroparin efficiently suppressed ERBB3 and AXL activity, comparably to loss of SLC35B2, further supporting HS dependency of ERBB3 and AXL signaling in melanoma cells." (PMID 35798875, 2022). "In PTC and melanoma, the upregulation of MET and ERBB3 expression level induced by BRAFi conferred BRAFi resistance to BRAFV600E mutant carcinomas, and inhibitors of MET and ERBB family could reserve the resistance to BRAFi effectively." (PMID 33613767, 2021). "Melanoma progression depends on activation of ERBB signaling, especially the ERBB3/ERBB2 cascade." (PMID 33732282, 2021). "In stage III melanoma patients, expression of BRD2/4 was strongly correlated with ErbB3." (PMID 31932756, 2020). "Furthermore, ErbB3 signalling induced by its natural ligand, neuregulin (NRG), is able to inhibit the differentiation of melanocytes, promoting the proliferation of melanoma cells." (PMID 31557826, 2019). "Increased expression of receptor tyrosine protein kinase erbB-3, also known as human epidermal growth factor receptor 3 (HER3), a member of the EGFR family of receptor tyrosine kinases, was described as a marker of poor prognosis in melanoma." (PMID 31717496, 2019). "One important mediator of adaptive resistance in mutant BRAF melanoma cells is the lineage-specific transcription factor, FOXD3, which undergoes rapid transcriptional induction upon inhibition of ERK1/2 signaling and activates the ERBB3/PI3K/AKT pathway." (PMID 29295999, 2018). "Additionally, ERBB3 up-regulation is also a mechanism of resistance to anti-BRAF therapies; and has been shown to promote melanoma metastasis." (PMID 28060735, 2017). "We show that melanoma cells orchestrate increased proliferation, invasion and migration using GH regulated intracellular signaling pathways and also upregulate oncogenic pathways like HGF-MET and ERBB3." (PMID 28223541, 2017). "Interestingly, we have recently shown that PI3K/AKT and NFκB are major survival pathways downstream ERBB3/2 in melanoma; and that lapatinib effectively inhibits ERBB2 and ERBB3 activation." (PMID 28060735, 2017). "Other adaptive signaling seen in melanoma cells within 24–48 hr involves an altered oxidative metabolism, increased phosphorylation of AKT, and upregulation of ERBB3." (PMID 26977879, 2016). "To investigate the role of SOX10, MITF, and FOXD3 and the reported effects due to BRAF status in ERBB3 regulation, we depleted the three former genes individually and in combination for MITF/FOXD3 by the use of siRNA in three melanoma cell lines: WM983B, MeWo and WM115." (PMID 27391157, 2016).
melanoma (continued). "This is supported by Abel and Aplin, who showed that FOXD3 does not regulate ERBB3 expression in BRAF wild-type melanoma cells, nor in melanocytes." (PMID 27391157, 2016). "CD271 knockdown was found to eliminate the capacity of melanoma cells to form heterogeneous tumors most likely through the downregulation of mediators for melanoma invasion and metastasis (GLI-2, SOX2 and ERBB3), angiogenesis (IGFBP-2), proliferation (FST and MITF) or chemoresistance (RHOJ)." (PMID 25351876, 2015). "In contrast to previous observations our data show in 10/11 melanoma cell lines that ErbB3 protein levels do not increase (both in vitro and in vivo) but that there is instead a selective enhancement of its phosphorylation." (PMID 26208478, 2015). "Moreover, in melanoma, thyroid and CRC the use of RAF and ERK inhibitors has been shown to result in removal of the feedback inhibition exerted on ErbB-3 transcription." (PMID 26160848, 2015). "In most patients, melanoma cells exhibited ErbB3/Her3, CD44/Pgp-1, ICAM-1/CD54 and IGF-1-R/CD221, but did not express CD20, ErbB2/Her2, KIT/CD117, AC133/CD133 or MDR-1/CD243." (PMID 24489649, 2014). "We therefore propose that identifying expression levels of MITF/SOX10, AXL/EGFR/ERBB3 prior to initiation of treatment may contribute to predicting treatment response to MAPK inhibitors and perhaps advice on drug combination strategies in melanoma." (PMID 36251678, 2023). "In line with this, and alike others, we observed that melanoma cells can undergo further dedifferentiation, losing neural crest features that are prominent in the intermediate state, such as expression of nerve growth factor receptor (NGFR), Erb-B2 receptor tyrosine kinase 3 (ERBB3), and SOX10." (PMID 36434616, 2022). "Moreover, the ERBB2/ERBB3 complex seems to be a promising target for combination tumor therapy in cutaneous melanoma, and activated NOTCH1 and ERBB2/ERBB3 signaling are involved in melanoma pathogenesis, supporting our data." (PMID 33786987, 2021). "Previous studies have shown that ErbB3 is a key factor in the development of adaptive resistance to BRAF and Mek inhibitors, albeit with different mechanisms, and that ErbB3 inhibition with monoclonal antibodies is able to potentiate the efficacy of target therapy in melanoma." (PMID 31557826, 2019). "We have recently shown that up to 70% of melanomas, regardless of whether they possess mutated or wild type BRAF, show hyper-activation of ERBB3 and rely on an ERBB3/ERBB2 signaling cascade to promote cell survival." (PMID 28060735, 2017). "Development of just a single ERBB3 peptide vaccine can be found in the literature however, peptide vaccines targeting ERBB1, ERBB2 or both ERBB1/2 including monoclonal antibody against tyrosine related protein 1 (TRP-1) and altered peptide sequence to gp100 for mouse melanoma all show promise." (PMID 28591206, 2017). "Moreover, activated ErbB3 has been observed in primary melanocytic lesions and this suggests that activation of NRG1/ErbB3 signaling may contribute to the progression of melanoma from benign nevi to metastatic malignancies." (PMID 22889873, 2012). "Interestingly, inhibitors of other classes of kinases relevant to melanoma such as vemurafenib, which target mutated BRAF, did not synergize with fucoidan, suggesting this natural compound amplifies the effects of inhibitors that target ERBB3 signaling." (PMID 28060735, 2017). "Importantly, ErbB3 activation is fully abrogated by the simultaneous use of anti-ErbB3 monoclonal antibodies, which are also shown to potently synergize with BRAF inhibitors in the inactivation of both AKT and ERK pathways and in the inhibition of melanoma cell growth." (PMID 23890105, 2013). "Additionally, we find that while ERBB3 and ERBB2 are affected by the treatment, EGFR was not, further reiterating our previous results that an ERBB3/ERBB2 signaling cascade operates in melanoma and is mostly responsible of the activation of PI3K/AKT signaling." (PMID 28060735, 2017).
melanoma (continued). "ERBB3 triggers survival cues to melanoma cells regardless of their oncogenic drivers; ERBB3 is also a mechanism of resistance to BRAF inhibitors; and promotes melanoma metastasis." (PMID 28060735, 2017).
gastric cancer (104 papers, 2006 to 2025). A primary or metastatic malignant neoplasm involving the stomach. "Recurrent ERBB3 mutations are observed in colon and gastric cancers and there are various studies on characterization of ERBB3 mutations in cancer." (PMID 38216592, 2024). "It has been shown that, over expression of ErbB1 and ErbB3, and ErbB4 proteins were significantly associated with poor prognosis in gastric cancer patients." (PMID 30621788, 2019). "We focused on the miRNAs associated SNPs in the 3′-UTR of ErbB3 to investigate the further relationship of the SNPs with miRNAs among Chinese gastric cancer (GC) patients." (PMID 28924391, 2017). "Recently, somatic mutations in ErbB3 with transforming potential were reported in colon and gastric cancers, however, these variants were still functionally dependent on ErbB2." (PMID 27447549, 2016). "In contrast, treatment of NCI-N87 gastric cancer cells resulted in loss of ERBB3 from the cell surface." (PMID 25386657, 2014). "Meanwhile, overexpression of ErbB1 has been correlated with gastric cancer, human hepatocellular carcinoma, and oesophageal cancer, and ErbB3 has been implicated in breast, bladder, and gastric cancers, whereas ErbB4 is also commonly associated with gastrointestinal cancer." (PMID 35800225, 2022). "ErbB3 mutations have recently been reported in ~11 % of colon and gastric cancers." (PMID 24643470, 2014). "This interplay between ERBB3 and SLC1A1 appears to involve HIF1α, which can be upregulated by heregulin and has been implicated in ferroptosis resistance in gastric cancer." (PMID 40846695, 2025). "Vice versa, ERBB3 inhibition with TX1-85-1 induced lipid peroxidation in gastric cancer cells, with effects most pronounced in cell lines expressing higher SLC7A11 levels." (PMID 40846695, 2025). "We treated five gastric cancer cell lines with the first reported selective ERBB3 inhibitor, TX1-85-1." (PMID 40846695, 2025). "This study is the first in gastric cancer to report that small-molecule inhibitors or siRNA-mediated knockdown of ERBB3 can induce lipid peroxidation." (PMID 40846695, 2025). "Overexpression of ERBB3 and ERBB1 mRNAs and proteins in histological specimens of gastric cancer has been significantly associated with tumor relapse and poorly differentiated morphology." (PMID 39858069, 2025). "A study of gastric cancer patients detected a high frequency of mutations in MLL4, ERBB3, FBXW7, MLL3, mtor(RPTOR), NOTCH1, PIK3CA, KRAS, ERBB4 and EGFR." (PMID 33909629, 2021). "In present study, we assessed the correlation between ErbB1 and ErbB3 co-overexpression (in the level of mRNA and protein expression) and gastric cancer prognosis for the first time." (PMID 30621788, 2019). "In this study, ErbB1 and ErbB3 expressions in the levels of mRNA and protein were assessed for the first time in gastric cancer cases to evaluate the probable role of ErbB1 and ErbB3 co-expression in gastric cancer prognosis." (PMID 30621788, 2019). "There was a direct correlation between EGFR and ErbB3 expression highlighting that these heterodimers have a significant prognostic role in gastric cancer." (PMID 30621788, 2019). "ErbB1 and ErbB3 expressions were analyzed by immunohistochemistry and real-time PCR in 50 patients with gastric cancer." (PMID 30621788, 2019). "ErbB1 and ErbB3 co-overexpression is accompanied with the poor prognosis and can be used efficiently in targeted therapy of gastric cancer patients." (PMID 30621788, 2019). "In the present study we assessed the probable correlation between concomitant EGFR and ErbB3 expression and prognosis in gastric cancer." (PMID 30621788, 2019).